KRTAP4-12 (keratin associated protein 4-12)
Description:
In the hair cortex, hair keratin intermediate filaments are embedded in an interfilamentous matrix, consisting of hair keratin-associated proteins (KRTAP), which are essential for the formation of a rigid and resistant hair shaft through their extensive disulfide bond cross-linking with abundant cysteine residues of hair keratins. The matrix proteins include the high-sulfur and high-glycine-tyrosine keratins.
Synonyms: KAP4.12; KRTAP4.12
Tractability: No criterion of Open Targets' tractability assessment is met for any kind of drug.
Gene: Protein-coding gene on chromosome 17 (41,123,091 to 41,124,182, reverse strand). Ensembl gene ENSG00000213416.
Gene Ontology:
Molecular function: protein binding
Biological process: hair cycle
Cellular component: cytosol; keratin filament
Genetic constraint (gnomAD): Loss-of-function variants: 3 observed, 3.59 expected, observed/expected ratio (o/e) 0.83, 90% interval 0.37 to 1.78. That is too few expected variants to judge how well the gene tolerates losing a copy. Missense variants: 240 observed, 264.85 expected, observed/expected ratio (o/e) 0.91, 90% interval 0.81 to 1.01. Synonymous variants: 85 observed, 90.09 expected, observed/expected ratio (o/e) 0.94, 90% interval 0.79 to 1.13.
Homologues: Orthologues: chimpanzee KRTAP4-12 (98% identical), mouse Krtap4-7 (64% identical), mouse Krtap4-24 (64% identical), rat Krtap9-7 (52% identical). Paralogues in human: KRTAP4-6 (93% identical), KRTAP4-11 (77% identical), KRTAP4-5 (77% identical), KRTAP4-9 (75% identical), KRTAP4-8 (70% identical), KRTAP4-7 (68% identical), KRTAP4-3 (64% identical), KRTAP4-4 (63% identical), KRTAP4-2 (56% identical), KRTAP4-1 (52% identical), KRTAP10-7 (49% identical), KRTAP10-4 (47% identical), and 35 more.